UGT1A9 (UDP glucuronosyltransferase family 1 member A9)
Diseases named in the same sentence as UGT1A9 in open-access papers (continued):
Sharing a sentence is not in itself a finding about the gene and the disease.
gastric cancer (1 paper, 2022). A primary or metastatic malignant neoplasm involving the stomach. "The UGT1A1*6 and UGT1A9*22 genotypes showed a higher prevalence in Korean gastric cancer patients, while the prevalence of the UG1A1*28 polymorphism was lower than in normal Koreans, as has been found in other studies of Asian populations." (PMID 36239106, 2022). "The UGT1A9*22 polymorphism showed similarly higher frequencies across Korean normal and gastric cancer patients (66.0%–64.1%, p = 0.876)." (PMID 36239106, 2022). "By genotyping UGT1A9*22 polymorphisms, we could identify high-risk gastric cancer patients receiving irinotecan-containing chemotherapy, who would experience severe toxicity." (PMID 36239106, 2022). "In this study, we analyzed the frequencies of important subtypes of UGT1A1, UGT1A7, and UGT1A9 in 382 Korean gastric cancer patients." (PMID 36239106, 2022). "In summary, our study shows a unique UGT1A genotype pattern in Korean gastric cancer patients and suggests that the presence of the UGT1A1*6, UGT1A7*3 and UGT1A9*22 polymorphisms in gastric cancer patients receiving irinotecan-containing treatment was significantly associated with severe toxicity." (PMID 36239106, 2022).
glomerulonephritis (1 paper, 2014). A renal disorder characterized by damage in the glomeruli. "Genotype analyses are not reported for the UGT1A9 polymorphisms that were planned due to their extremely low frequency in this glomerulonephritis population." (PMID 24548980, 2014).
kidney cancer (1 paper, 2015). Primary or metastatic malignant neoplasm involving the kidney. "From the unique set of genes detected by CANOVA, a few were reported to be relevant to kidney cancer/disease: FAH, MCM3 and UGT1A9." (PMID 26283601, 2015).
kidney damage (1 paper, 2025). "In the metabolic transformation and transport process of kidney transplantation, especially in the context of cyclosporine metabolism, genetic variations in the Ugt1a9 gene may lead to kidney damage." (PMID 39931687, 2025).
liver disease (1 paper, 2014). "There was no change in the Km values of sorafenib for the two groups, suggesting that liver disease did not change the UGT1A9 enzyme’s affinity for sorafenib." (PMID 24797816, 2014).
non-alcoholic fatty liver disease (1 paper, 2024). "Similarly, the progression of human non-alcoholic fatty liver disease (NAFLD) is accompanied by a selective upregulation of certain UGT isoforms, notably UGT1A1, UGT1A3, UGT2B10, and UGT1A9." (PMID 38790653, 2024).
cancer (16 papers, 2012 to 2025). A tumor composed of atypical neoplastic, often pleomorphic cells that invade other tissues. "The association of UGT1A9 rs6714486 with lower cancer incidence in our study coincides with the data of other authors that recently correlated this variant with mycophenolate mofetil efficacy." (PMID 35214086, 2022). "We observed associations between exitus and genetic variants in MTHFR metabolizer gene, as well as between a decreased risk of de novo cancer and variants in UGT1A9 metabolizer gene." (PMID 35214086, 2022). "In our study, the TA variant in UGT1A9 was associated with a lower incidence (HR: 0.13) of de novo cancer." (PMID 35214086, 2022). "In our cohort, we found that survival rate was associated with gene variants in MTHFR, and cancer incidence risk was associated with genotype in UGT1A9 metabolizer gene." (PMID 35214086, 2022). "In addition, donor polymorphisms in UGT1A9 metabolizer gene rs6714486 (OR: 0.13; p-value: 0.032) were associated with a lower risk of suffering from de novo cancer." (PMID 35214086, 2022). "Besides, UGT1A9 intronic 1399 C>T polymorphism enhanced SN-38 glucuronidation in Asian cancer patients." (PMID 24797816, 2014). "Reduced activity of UGT1A9 often induces the adverse effects of drugs, such as the problematic for patients undergoing cancer treatment using irinotecan/SN-38 resulted from the low activity of UGT1A9." (PMID 28466663, 2017). "UGT1A1 and UGT1A9 enzymes metabolize SN-38, the active form of the cancer drug irinotecan." (PMID 40432911, 2025). "In a study of 84 Japanese cancer patients, comprising 50 with colon cancer, 18 with stomach cancer, seven with ovarian cancer, seven with lung cancer, and two with other types of cancer, a genetic association between UGT1A7 and UGT1A9 polymorphisms and the UGT1A1-6 allele was reported." (PMID 40432911, 2025). "UGTs genes are upregulated in tissues associated with drug metabolism, such as cancers of the liver, kidney, intestine, and pancreas, such as UGT1A6, UGT1A9, UGT1A10, UGT2A3, UGT2B7, and UGT8, and they are significantly associated with increased overall survival in cancer." (PMID 36741721, 2022). "As canagliflozin is metabolized and excreted by UGT1A9 and UDP glucuronosyltransferase family 2 member B4 (UGT2B4), we speculate that cancer cells expressing SGLT2 combined with low levels of UGT1A9 and UGT2B4, will make these tumor cells sensitive to canagliflozin." (PMID 31979355, 2020). "As the adhesion-blocking effect of dapagliflozin on cancer cells was only demonstrated in HCT116 cells while other cancer cell types tested were resistant to such effects, the expression of SGLT-2 and UGT1A9 was examined in all these cell types." (PMID 36497303, 2022). "The results of this study indicated that the anti-adhesion effect of dapagliflozin in relation to cancer cells depends on the expression levels of SGLT-2 and UGT1A9." (PMID 36497303, 2022). "In Japanese cancer patients, UGT1A1*28, UGT1A9*1b, UGT1A1*6 (211G > A), and UGT1A1*60 (3279 T > G) are closely associated with the UGT1A9 IVS1 + 399 (I399C > T) polymorphism, and linkage of I399C > T with these variants has been shown to affect irinotecan metabolism." (PMID 24650752, 2014). "In contrast, the presence of high levels of UGT1A activity, in particular UGT1A9 activity, may break this cycle and promote the metabolic elimination of TSA in cancer cells." (PMID 24244442, 2013). "In both cases, SGLT2 staining was positive in the cancer cells, but UGT1A9 was relatively negative." (PMID 31979355, 2020).
tumor (9 papers, 2014 to 2024). "After FDR p-value correction employing p-values of the different gene variants selected, only the TA variant in UGT1A9 rs6714486 of the recipient was significantly (p = 0.032) related to lower tumor probability (HR: 0.13)." (PMID 35214086, 2022). "Correspondingly, the relative protein expression level of UGT1A9 was dramatically decreased in tumor HLMs compared to the adjacent normal HLMs, especially in P1-06161 with the reduction of 99.91%." (PMID 26010150, 2015). "By utilizing increasing concentration of propofol (from 37.5 μM to 1000 μM), the significant decreasing metabolic activities of UGT1A9 were found in five individual tumor and the adjacent normal HLMs (P < 0.01)." (PMID 26010150, 2015). "Whereas UGT1A9 metabolic activities was only significantly related to protein expression ratio in HBV-positive HCC tumor tissues (R2 = 0.811, P < 0.001)." (PMID 26010150, 2015). "However, the levels of UGT1A9 were substantially reduced in the tumor compared to the healthy tissue." (PMID 31979355, 2020). "However, opposite differences of gene expression ratio between tumor and the adjacent normal tissues were also present, specifically, the gene expression level of UGT1A9 was notably increased in P2-07271 (452.63%, P < 0.001), while that of was significantly decreased in P5-12221 (90.86%, P < 0.001)." (PMID 26010150, 2015). "Sorafenib metabolism was shown to be significantly decreased in tumor hepatic microsomes together with the downregulation of CYP3A4 and UGT1A9 expression." (PMID 36035299, 2022). "By utilizing certain specific substrates for UGTs, we initially demonstrated that catalytic activities of UGT1A, UGT1A1, UGT1A4, UGT1A9 and UGT2B7 were significantly decreased in the tumor tissues in HBV-positive HCC patients." (PMID 26010150, 2015). "Therefore, our study aims to determine whether CYP3A4- and UGT1A9-mediated sorafenib metabolism is differentially affected in HCC patient tumor hepatic microsomes (THLMs) in comparison with those in adjacent normal hepatic microsomes (NHLMs) and commercial hepatic microsomes (CHLMs)." (PMID 24797816, 2014). "Given the increasing incidence and mortality of HCC with the high HBV-infection background in China, we systematically analyzed the metabolic function, protein and gene expression levels of UGT1A, UGT1A1, UGT1A9, UGT1A4 and UGT2B7 in HBV-positive HCC tumor and the adjacent normal tissues." (PMID 26010150, 2015). "The results revealed that in the tumor human liver microsomes (HLMs), either Vmax (maximum reaction rate, Rmax for UGT1A1) or the clearance rates (Vmax/Km, Clint) of UGT1A, UGT1A1, UGT1A4, UGT1A9 and UGT2B7 were significant lower than those of in the adjacent normal HLMs." (PMID 26010150, 2015). "Although the metabolic activity and expression level of CYP3A4 and UGT1A9 were low exclusively in THLMs but not in NHLMs in our patients, the plasma concentrations of sorafenib and its metabolites probably depend on the volume of HCC tumor tissue and/or the surrounding cirrhotic tissue." (PMID 24797816, 2014).
infection (1 paper, 2019). The state of being infected such as from the introduction of a foreign agent such as serum, vaccine, antigenic substance or organism. "On the other hand, Cyp1a2, Cyp3a25, Ugt1a6 and Ugt1a9, although down-regulated at 8 days post-infection, showed minimal effects at 6 and 12 days post-infection." (PMID 31299982, 2019).
UGT1A9 also shares sentences with these, for which no sentence is quoted: epilepsy (3 papers); breast carcinoma (2); diabetes mellitus (2); acute liver failure (1); Anxiety (1); atopic dermatitis (1); bacterial infection (1); bladder cancer (1); cholelithiasis (1); coronary heart disease (1); diarrheal disease (1); fatty liver (1); Hepatitis (1); Hypercholesterolemia (1); Hyperinsulinemia (1); ischemic stroke (1); kidney disease (1); lung carcinoma (1); metabolic disorders (1); mood disorder (1); mucinous adenocarcinoma (1); ovary cancer (1); papillary thyroid cancer (1); prostate carcinoma (1); renal cell carcinoma (1); respiratory infection (1); type 2 diabetes mellitus (1); viral disease (1).